FGF21 (fibroblast growth factor 21)
Diseases named in the same sentence as FGF21 in open-access papers (continued):
Sharing a sentence is not in itself a finding about the gene and the disease.
Insulin resistance (continued). "Therefore, digenic variants in FGFR1 and KLB provide a potential explanation for the subject’s severe insulin resistance and may represent a novel category of insulin resistance syndromes related to FGF21." (PMID 33210059, 2020). "Thus, the increased expression of hepatic Sdf2l1 and FGF21 via htr2a might be related to insulin resistance in mice fed a high-fat diet." (PMID 32978487, 2020). "Therefore, resistance to FGF21 may explain the proband’s severe insulin resistance and tall stature." (PMID 33210059, 2020). "Moreover, the level of FGF21 correlated with insulin resistance." (PMID 31847236, 2019). "Thus, we investigated whether FGF21 involved in macrophage polarization that may protect adipocytes from inflammation which contributes to insulin resistance." (PMID 29348470, 2018). "Therefore, targeting Dnmt3a or Fgf21 could provide new treatment opportunities for obesity-related complications such as insulin resistance." (PMID 29239299, 2017). "The central role of fat tissue to FGF21 function was demonstrated in a lipoatrophic mouse model (mice severely depleted of adipose tissue), where recombinant FGF21 treatment cannot correct the hyperglycemia and insulin resistance in these mice in contrast to wild-type animals." (PMID 26594197, 2015). "Their findings, together with the non-significant result of our work, led us to postulate that circulating FGF21 may be associated with insulin resistance but not insulin itself." (PMID 26540514, 2015). "Given the relationship between insulin resistance and PE, the role FGF21 plays may be critical." (PMID 25890271, 2015). "Similarly, the treatment of diabetic monkeys with FGF21 corrected insulin resistance and improved β-cell function.These data indicates that FGF21 may serve as promising targets for the treatment of type 2 diabetes mellitus (T2DM)." (PMID 26540514, 2015). "Fgf21 expression in skeletal muscle, but not serum FGF21 levels was increased in HIV patients with lipodystrophy and this was correlated to insulin resistance, indicating that FGF21 is a myokine that may be correlated with insulin resistance in an autocrine/paracrine manner." (PMID 25071723, 2014). "The recent findings on FGF-21 ability to prevent insulin resistance in human myoblasts by inhibiting NF-κB activation may also suggest that the muscle-derived FGF-21 acts in an autocrine fashion to amplify PPAR-δ inhibitory effects on the expression of NF-κB-dependent inflammatory genes." (PMID 23861559, 2013). "Also, elevated fasting plasma FGF-21 levels were decreased (1.60±0.08 vs. 1.30±0.05, P<0.05) concomitant with ameliorations in insulin resistance and β-cell dysfunction, which were shown by a significant decrease in HOMA-IR values and a significant increase in HOMA-IS values (both P<0.01)." (PMID 22046277, 2011). "Hence, the regulation of circulating FGF-21 might be influenced by metabolic control, insulin resistance and β cell function." (PMID 22046277, 2011). "While some (such as FGF-21, irisin, adiponectin, klotho, and osteocalcin) have protective effects, others (such as myostatin, fetuin-A, visfatin, and ANGPTL3) exacerbate insulin resistance, inflammation, and fibrosis." (PMID 41373697, 2025). "Since hyperglycemia, insulin resistance, and hyperlipidemia are key contributors to the onset and progression of DCM in T2D, FGF21 likely treats DCM by targeting these metabolic disorders." (PMID 40724827, 2025). "When the insulin signaling pathway is impaired, FGF21 enhances insulin signaling by activating the AMPK signaling pathway and inhibiting the mTOR signaling pathway to achieve glucose uptake and improve insulin resistance." (PMID 40881124, 2025). "For instance, a study on insulin-resistant mice found that long-term FGF21 treatment activated the FAO signaling pathway, leading to improved cardiac metabolism, reduced insulin resistance, enhanced FGF21 sensitivity, and better overall cardiac function." (PMID 40036545, 2025).
Insulin resistance (continued). "In this study, we found that impaired FGF21 signaling in GDM correlates with worsened inflammation and insulin resistance in white adipose tissues in mice." (PMID 39599611, 2024). "Fibroblast growth factor 21 (FGF21) is a peptide hormone that regulates energy homeostasis and is increased in ischemic heart disease, type 2 diabetes, insulin resistance, and dyslipidaemia where it has been shown to act as a compensatory reaction." (PMID 38932813, 2024). "Studies have shown that fibroblast growth factor 21 (FGF21) improves hyperlipidemia and insulin resistance and increases energy expenditure in obese animals, leading to weight loss." (PMID 39478961, 2024). "The fibroblast growth factor 21 (FGF-21) can improve insulin sensitivity and insulin resistance and can be used in type II diabetes." (PMID 37951928, 2023). "On the other hand, it has been suggested that adiponectin and fibroblast growth factor-21 (FGF-21) levels increase after HCHFD and inhibit lipid accumulation and insulin resistance in muscle and the liver to compensate for lower insulin resistance." (PMID 37373776, 2023). "What’s worse, FGF21 LKO even further exacerbated whole-body glucose metabolic dysfunction as evidenced by more impaired glucose and pyruvate tolerance and worsened insulin resistance." (PMID 37834368, 2023). "In mouse models of mild mitochondrial stress, chronically elevated FGF21 and GDF15 provide resistance to DIO and insulin resistance and ameliorate diet-induced hepatic steatosis and glucose intolerance." (PMID 37818094, 2023). "Furthermore, FGF-21 could enhance adiponectin with its activity against insulin resistance." (PMID 37892985, 2023). "The mRNA expression of NF-κB, AKT, ATG7, and FGF21 in the liver tissue was analyzed to confirm the effects of MGF on the linkage of autophagy and insulin resistance, and the current results explained that MGF decreased inflammation and regulated autophagy." (PMID 36499655, 2022). "This reveals crosstalk at the hypothalamic level involving resistin, insulin, adiponectin, and FGF21 signaling pathways, which would be involved in HFD-induced neuroinflammation and insulin resistance." (PMID 36078135, 2022). "FGF21 level increased in T2DM and is positively correlated with hyperglycemia, insulin resistance and inflammatory processes." (PMID 36457562, 2022). "This situation was mimicked in our patients with solid correlations with glucose homeostasis parameters, especially FGF21, fasting insulin, and HOMA1-IR, the latter two reflecting whole-body insulin resistance." (PMID 35160008, 2022). "An earlier study evaluated FGF-21 levels in PCOS and found that circulating FGF-21 levels were higher in PCOS patients and correlated with homeostasis model assessment insulin resistance index (HOMA-IR)." (PMID 35574015, 2022). "FGF21 is one of the most potent insulin sensitizers and since insulin resistance is one of the most important factors in NAFLD development, FGF21 with this mechanism can ameliorate NAFLD." (PMID 36457562, 2022). "At baseline, the postprandial FGF21 response was inversely correlated to insulin resistance as estimated by HOMA-IR, with more insulin resistant individuals exhibiting a larger postprandial decline in plasma FGF21 compared to insulin sensitive individuals." (PMID 36501091, 2022). "Fibroblast growth factor 21 (FGF21) is a member of the family of endocrine fibroblast growth factors, whose beneficial effects on glucose, lipid metabolism and insulin resistance were found in early studies." (PMID 35437883, 2022). "Further, exercise-mediated changes in serum FGF21 and GDF15 correlated with changes in the homeostasis model of assessment of insulin resistance (HOMA-IR) and appendicular lean mass (ALM), respectively." (PMID 33668309, 2021).
Insulin resistance (continued). "Previous studies have found that a variety of hepatokines play an important role in the occurrence and development of insulin resistance and T2DM, including fibroblast growth factor 21 (FGF21), retinol binding protein 4 (RBP4), and fetuin A." (PMID 34858327, 2021). "Taken together, reduced levels of FGF21 and adiponectin provide attractive mechanisms for the links between SCI and insulin resistance and T2DM." (PMID 34046014, 2021). "The FGF21 therapy decreased fasting insulin levels and HOMA-IR, suggesting an improvement in insulin resistance." (PMID 32957703, 2020). "Recently, obesity-induced hypermethylation at adiponectin and Fgf21 genes mediated by DNMT1 and DNMT3A, respectively, was shown to play an important role in the pathogenesis of insulin resistance in adipose tissue." (PMID 33235221, 2020). "We assessed whether plasma concentrations of three known myokines [myonectin, myostatin, and fibroblast-derived growth factor 21 (FGF-21)] would be associated with direct and indirect indicators of insulin resistance (IR) in individuals who did not have a diagnosis of diabetes." (PMID 29445355, 2018). "FGF21, which is an endocrine member of FGF family, is involved in improvement of insulin resistance and glucose metabolism." (PMID 28288167, 2017). "Therefore, FGF21, a mainly liver-derived cytokine, was found to be associated with the occurrence of CAD in this study, which might be explained, concerning the mechanism, by the involvement of insulin resistance." (PMID 23981342, 2013). "Here, we examined the relationships between adiposity and insulin resistance and circulating levels of adiponectin, FABP4, lipocalin-2, PAI-1 and FGF21 before and after high fat overfeeding for 28 days." (PMID 24205333, 2013). "Considering the glucose- and insulin-lowering actions of FGF19 and/or FGF21 in diabetic rodents, the potential of FGF19 and/or FGF21 treatment to ameliorate impaired glucose tolerance and insulin resistance in GDM patients warrants future attention." (PMID 24260557, 2013). "BM supplementation resulted in reduction of liver FGF21expression and induction of its receptor expression in the HFD fed mice, indicating that BM extract enhances FGF21 signaling, by which attenuates HFD-induced insulin resistance and hepatic steatosis." (PMID 24189525, 2013). "However, unlike FGF21, Klotho causes insulin resistance, which may limit its utility as a therapeutic agent." (PMID 23066506, 2012). "Although it remains unclear whether serum FGF21 levels are increased by FGF21 resistance or an adaptive response to metabolic disorders, these findings indicate that FGF21 potentially functions as a metabolic regulator in relation with insulin resistance and is a biomarker for metabolic diseases." (PMID 21331285, 2011). "The activity of FGF19 to improve insulin resistance and hyperglycemia in obese and diabetic mice is shared by a related endocrine FGF, FGF21." (PMID 21437243, 2011). "Serum FGF21 levels are also markedly increased in patients with ESRD, suggesting FGF21 to play a role in insulin resistance in these patients." (PMID 21331285, 2011). "As hyperglycemia, insulin resistance, and hyperlipidemia are major contributors to DCM in T2D, we further explored whether FGF21 could mitigate heart damage in T2D mice." (PMID 40724827, 2025). "Given that leptin levels are increased in MASLD patients, and leptin promotes insulin resistance, we consider the negative relationship between FGF21 and LEPR as highly suggestive for FGF21 to improve insulin sensitivity by dampening leptin signalling." (PMID 39962359, 2025). "FGF21 and GDF15, as sensitive indicators of mitochondrial stress, are increasingly recognized for their potential to bridge interconnected pathways involving oxidative stress, chronic inflammation, and insulin resistance in cardiovascular disease research." (PMID 41234361, 2025).
Insulin resistance (continued). "In rodents and non-human primates, FGF21 treatment has beneficial effects on cardiometabolic outcomes, such as reduction in fat mass and alleviation of hyperglycaemia, insulin resistance, dyslipidaemia, and cardiovascular diseases." (PMID 40308270, 2025). "Importantly, simultaneous deletion of Fgf21 and Gdf15 in BAT significantly attenuated the resistance to DIO and insulin resistance in OPA1 BKO mice." (PMID 40897647, 2025). "Notably, combined Fgf21 and Gdf15 deletion in OPA1 BKO significantly blunted the resistance to DIO and insulin resistance observed in OPA1 BKO mice." (PMID 40897647, 2025). "In addition to FGF21, thiazolidinediones can also increase FGF1 expression by activating PPAR-γ, similarly avoiding the appearance of insulin resistance." (PMID 38884020, 2024). "The phosphorylation of mitogen-activated protein kinase by FGF21 mediates activation of mTORC1/SK6 signaling and promotes the expression of the downstream effector gene GLUT1, which promotes glucose uptake and alleviates insulin resistance." (PMID 38069273, 2023). "Like other authors, we have not observed FGF21 to be correlated with insulin levels when analyzing insulin resistance markers." (PMID 37869250, 2023). "Multiple studies have shown that FGF21 can alleviate insulin resistance, but interestingly, the synergistic effect of FGF21 and insulin is not negligible." (PMID 38069273, 2023). "FGF21 treatment did not significantly alter changes in insulin resistance, and the change in HOMA-IR between the groups was not significantly different following the treatment period (p = 0.88), consistent with both insulin and glucose." (PMID 36756310, 2023). "Dietary methionine restriction targets fibroblast growth factor 21 (FGF-21), protein phosphatase 2A (PP2A), and autophagy, which further improves insulin resistance, insulin sensitivity, and reduces diabetes-related complications partially due to reduction in ROS production." (PMID 36714968, 2023). "Fibroblast growth factor 21 (FGF21) is a member of the human FGF superfamily and is a key protein involved in the maintenance of metabolic homeostasis, including reducing fat mass and lowering hyperglycemia, insulin resistance and dyslipidemia." (PMID 37576954, 2023). "Potentially, insulin resistance and dyslipidemia were not severe enough in our cats for FGF21 pathway activation to significantly affect the treatment group." (PMID 36756310, 2023). "Therefore, we aimed to explore the possibility of using fibroblast growth factor 21 (FGF-21), free fatty acids (FFAs), homeostatic model assessment for insulin resistance (HOMA-IR), and quantitative insulin sensitivity check index (QUICKI) as possible markers." (PMID 38222178, 2023). "This suggests that FGF21 drives lipolysis of the adipose tissue stores without a change in adipose insulin resistance." (PMID 36756310, 2023). "These authors created a nanosystem able to transfect two plasmids: the fibroblast growth factor 21 (FGF-21, known to improve glucose metabolism and insulin resistance) and Liraglutide, an analog of the Glucagon-like peptide-1 (GLP-1) with a hypoglycemic effect." (PMID 36839672, 2023). "It remains unclear whether FGF21 and TSK can regulate each other in connection with insulin resistance." (PMID 35323680, 2022). "GDF15 levels correlated with LDL cholesterol, PUFA, MUFA, FGF21, and insulin resistance, even after age adjustment, whereas they did not correlate with triglycerides, HDL cholesterol, or non-HDL cholesterol." (PMID 35160008, 2022). "Plasma levels of both FGF21 and GDF15 are known to be increased in obese humans and rodents as well as in other metabolic disease states such as insulin resistance, NAFLD and mitochondrial disease." (PMID 36064109, 2022). "In HFD fed mice, FGF21 increases insulin-stimulated AKT phosphorylation and glucose uptake in the skeletal muscle, while in human skeletal muscle myotubes, FGF21 prevents palmitate-induced insulin resistance." (PMID 35409319, 2022).
Insulin resistance (continued). "Fibroblast growth factor 21 (FGF21), which is a stress-inducible peptide hormone that regulates energy balance and glucose and lipid homeostasis, has been proven to alleviate hyperglycemia, insulin resistance, dyslipidemia and fatty liver." (PMID 36290791, 2022). "We studied the effects of IT protocol on RBP4, aHSG/fetuin-A, FGF21, and CRP levels, liver histology, HOMA-IR as well as total lipid content in the obese Zucker (Crl:ZUC(ORL)-Leprfa) rats—an animal model of insulin resistance, glucose intolerance, metabolic syndrome, and genetic obesity." (PMID 33833309, 2021). "The results showed that FGF21 and GLP1 gene-modified MSCs could significantly improve insulin resistance and promote β-cell function recovery." (PMID 33588950, 2021). "Serum FGF21 levels were tested for correlation with anthropometric and metabolic parameters; glucose, cholesterol, HDL, LDL, VLDL, triglycerides, insulin and indexes of atherogenesis and insulin resistance (HOMA)." (PMID 34019585, 2021). "Hamsters in the LD state offer the possibility of studying the actions of FGF21 in fat animals without the confounding effects of the development of insulin resistance." (PMID 31918921, 2020). "Moreover, BAFF−/− mice showed enhanced leptin and FGF21 production, which provides another explanation for the improving effect of BAFF depletion on insulin resistance." (PMID 32698539, 2020). "It has been described that patients with type 2 diabetes have elevated levels of circulating FAP compared with nondiabetic subjects, thus suggesting that insulin resistance led to an inactivation of FGF21 and to the attenuation of its beneficial effects." (PMID 31546675, 2019). "While a LCD that increases FGF21 serum levels is able to ameliorate glucose and insulin tolerance in diabetic mice, a very-low carbohydrate diet fails to improve whole-body insulin resistance in rats." (PMID 31546675, 2019). "The animal studies suggested that there are some mechanisms involved in FGF21-mediated alleviation of endothelial dysfunction that are independent of reducing hyperglycemia and improving insulin resistance." (PMID 31511499, 2019). "Fgf21 knockout mice show less subcutaneous WAT and a greater degree of insulin resistance." (PMID 30804796, 2019). "Fibroblast growth factor 21 (FGF21) is a liver-derived circulating hormone that has emerged as an important regulator of glucose and lipid metabolism, making it a promising agent for the treatment of insulin resistance and type 2 diabetes mellitus." (PMID 29558390, 2018). "Finally, another study revealed that FGF21 knock-out mice fed a KD develop NAFLD and severe hepatic insulin resistance as assessed by the gold-standard technique, the hyperinsulinemic-euglycemic clamp." (PMID 28534852, 2017). "The FGF21 levels in this study were positively correlated to the level of insulin resistance in these dialysis patients independent of residual renal function, indicating that the regulation of FGF21 is complex." (PMID 25890271, 2015). "Therapeutic administration of recombinant FGF21 exerts a variety of beneficial effects in rodents and nonhuman primates, including reduction of adiposity and alleviation of hyperglycemia, insulin resistance, dyslipidemia, and fatty liver disease." (PMID 25991671, 2015). "In animal experiments, it is shown that, by suppressing PPAR-alpha and fibroblast growth factor 21, BDNF might facilitate insulin resistance and dyslipidemia and thus has antidiabetic and lipid lowering effects." (PMID 25587547, 2014). "Our findings suggest that MR feeding can reverse the negative effects of aging on body mass, adiposity, and insulin resistance through an FGF21 mechanism." (PMID 24935677, 2014). "FGF-21 mRNA is increased in skeletal muscle in HIV patients and correlates to whole-body (primarily reflecting muscle) insulin resistance, but not to plasma FGF-21." (PMID 23533568, 2013).